ATF6 (activating transcription factor 6)
Diseases named in the same sentence as ATF6 in open-access papers (continued):
Sharing a sentence is not in itself a finding about the gene and the disease.
tumor (continued). "We next evaluated the Spearman correlation between SCNA score and parent genes for the three branches of the UPR (IRE1α, PERK, and ATF6) across all thirty‐two tumor types in TCGA." (PMID 34698427, 2021). "We found that the survival rate of patients was lower, and that the proliferation and aggressiveness of tumor cells were stronger in PC when ATF6 expression is elevated." (PMID 35222510, 2021). "The size of the xenograft tumor in EtOH-fed mice is larger than in the control group, as well as the expression of intranuclear ATF6." (PMID 34521429, 2021). "We found that the expression of LC3B and ATF6 appeared to be positively correlated with ID1 expression in xenograft tumor tissues." (PMID 32080166, 2020). "We also confirmed that the siRNA-mediated loss of ATF6 expression induced an obvious decrease in the number of VEGFR+ vascular endothelial cells and the tumor expression of pEGFR." (PMID 32630838, 2020). "Collectively, these results suggest that ATF6-mediated EGF expression in SCCs is a target with which to block tumor recurrence." (PMID 32630838, 2020). "Additional preclinical and clinical studies are also required to evaluate the effectiveness of targeting the ATF6-EGF-signaling cascade in suppressing tumor recurrence." (PMID 32630838, 2020). "Till date, there are several ER stress inhibitors such as ATF6 inhibitor that were reported to display a strong effect on tumor migration inhibition of large range of cancer types including brain, breast, liver, lung, pancreas and skin." (PMID 33014334, 2020). "To validate this result, we analyzed the expression of ID1, LC3B, and ATF6 in xenograft tumor tissues derived from previously conducted animal experiments." (PMID 32080166, 2020). "The levels of LC3B and ATF6 were increased in xenograft tumor tissues from animals injected with HEY-ID1 and HEY A8-ID1 but were decreased in SKOV3 ip1-ID1i cells, compared with control tissues." (PMID 32080166, 2020). "Expression of PERK and ATF6 significantly correlated with tumor stage (Stages I through IV: p < 0.0001); GRP78 expression also correlated with early tumor stages Stages I and III (p < 0.001) but not with Stage II and IV." (PMID 32034256, 2020). "Some evidences also showed that ATF6 plays an important role on cell dormancy in rapamycin-treated tumours." (PMID 32111004, 2020). "The third UPR branch, ATF6 signaling pathway, has been reported to play a role in disease recurrence and tumor growth." (PMID 32034256, 2020). "Additional studies further demonstrated that ATF6 ablation using liposome-encapsulated ATF6 siRNA reduced angiogenesis-stimulating activities in SCCs and thus suppressed tumor recurrence." (PMID 32630838, 2020). "Little has been described so far on the potential role of ATF6 in modulating tumor cell migration/invasion." (PMID 31064137, 2019). "Knockdown of ATF6α prolonged the survival of nude mice bearing dormant tumor cells through the ATF6α-Rheb-mammalian target of rapamycin (mTOR) pathway in a p38-dependent manner." (PMID 30857233, 2019). "Using germ-free mice, we showed that ATF6-activated UPR in the epithelium requires the presence of intestinal microorganisms for tumor formation." (PMID 31867005, 2019). "In contrast, downregulation of the ATF6 pathway promoted cell death and reversed the resistance of the dormant tumour cells to rapamycin and glioblastoma cells to radiation." (PMID 29415493, 2018). "ATF6 staining was generally strong in the neoplastic lesions: the median ATF6-IHC score in 43 samples of neoplasia was 6.0 (range, 2–11), which was significantly higher (p < 0.001) than that in 93 samples without neoplasia (median, 3.0, range, 0–11)." (PMID 28884228, 2018).
tumor (continued). "Multivariate analysis revealed that a combination of high expression of ATF6α and a low expression of phospho-P38 was associated with a poor outcome for PDAC patients (HR = 2.705; p = 0.023), together with tumour grade (HR = 2.886; p = 0.029)." (PMID 30134550, 2018). "Concerning other types of tumours, a high expression of ATF6α has been involved in chemoresistance of leukemia-derived cell lines to imatinib, and it was necessary for the survival of melanoma-derived cell lines under ER stress conditions." (PMID 30134550, 2018). "Overexpression of IP10 promoted HCC cell proliferation and tumor growth under cisplatin treatment by activation of ATF6/Grp78 signaling." (PMID 26336986, 2015). "In normal conditions, ATF6α is linked to glucose-regulating protein 78 (GRP78), but in ER stress, which is critical for tumor cells, both proteins dissociate." (PMID 26559273, 2015). "In the cases with high expression, ATF6α was also detected in the nucleus of some stromal cells, although most of the cases showed stronger staining in tumor cells than in stroma." (PMID 26559273, 2015). "ATF6α staining had not only basically nuclear localization but also was diffusely detected in the cytoplasm of tumor cells." (PMID 26559273, 2015). "Expression of GRP78, which is upregulated by the ATF6 signaling during ER stress, has been shown to be essential for tumor growth, survival, progression, and metastasis." (PMID 25941664, 2015). "Our view was supported by the finding of considerable amounts of the 50 kD-fragment of the stress sensor ATF6 in protein extracts of sparsely grown tumor cells." (PMID 24498091, 2014). "The highest relative expression of ATF6 showed tumours classified into the group 1 (0.210 ± 0.0014), whereas the lowest expression showed tumours classified into the group 2 (0.012 ± 0.0014)." (PMID 23587192, 2013). "The relative expression of ATF6 differed significantly between tumours classified into the groups 1 and 2 (p < 0.05)." (PMID 23587192, 2013). "In another tumour cell line, upregulation of the ATF6α transcription factor promoted survival of dormant tumour cells in nude mice." (PMID 22724067, 2012). "LS3x showed 3-fold over-expression of both genes, and for LMS2x and MFH19, DUSP12 was over-expressed 2–3 fold whereas ATF6 was expressed at the same level as the three tumours with normal copy number." (PMID 16274472, 2005). "DUSP12 was expressed significantly higher than ATF6 in these two tumours (p < 0,001 for MS8x and p < 0,01 for LS21), and also in LMS2x and MFH19 (both p < 0,001)." (PMID 16274472, 2005). "TRIM37 overexpression counteracted ATF6 knockdown’s impact on tumor growth in vivo." (PMID 40158112, 2025). "TRIM37 overexpression counteracts ATF6 knockdown’s impact on tumor growth in vivo." (PMID 40158112, 2025). "In the context of cancer, ATF6 plays a dual role in promoting tumor growth and metastasis." (PMID 40223122, 2025). "Lastly, ATF6 ad a key regulator in the term of unfolded protein response, when downregulated, may impair cellular stress responses in the tumor microenvironment, contributing to tumor cell survival." (PMID 41411347, 2025). "The UPR pathways-PERK, IRE1α, and ATF6 may modulate immune cell function within the tumor microenvironment." (PMID 40978046, 2025). "GRP78 is a well-documented target of ATF6α and plays a crucial role in tumor metastasis." (PMID 40223122, 2025). "What remains to be elucidated, is how ATF6 signalling induces dysbiosis at the pre-tumour stage." (PMID 40890536, 2025). "However, microbial contributions differed greatly, with mostly zOTUs classified as Parabacteroides and Romboutsia, indicating the presence of tumours differentially modulates microbiota, compared to Atf6 activation alone." (PMID 40890536, 2025).
tumor (continued). "The dichotomous relationship pro- and anti-tumor effects of IRE1α and ATF6 warrant scrutiny to ensure that biomarker-driven strategies are advanced judiciously in specific cancer populations such that cancer pro-survival pathways are not triggered accidentally." (PMID 41301006, 2025). "Moreover, subsets of OS cells exhibit activation of the unfolded protein response (UPR), with ATF6α identified as a key contributor of tumor malignancy." (PMID 41154810, 2025). "Research showed that activation of UPR may lead to the suppression of surface expression of MHC class I (MHC-I) molecules, which is mediated by the upregulation of X-box binding protein 1s(XBP1s) and ATF6, ultimately resulting in immune evasion by tumor cells." (PMID 38229155, 2024). "High-throughput single-cell RNA sequencing (scRNAseq) revealed that PAZ@Fe-MOF significantly reduced pro-tumorigenic M2-like macrophage populations at tumor sites and suppressed M2-type signaling pathways, such as ATF6-TGFBR1-SMAD3, as well as chemokines including CCL17, CCL22, and CCL24." (PMID 39033109, 2024). "Indeed, an increasing number of studies have shown the role of UPR signaling, which is driven namely by IRE1, PERK, and ATF6, in different aspects of carcinogenesis and tumor progression." (PMID 38591121, 2024). "In response, the sustained activation of IRE1α and ATF6 branches driven by MEK/ERK pathway endows tumor cells with enhanced survival capacity, with the involvement of the activation of downstream autophagy, mitochondrial fission, mitophagy and JAK/ STAT3 pathway." (PMID 38291473, 2024). "The majority of current researches on ATF6 in cancer have concentrated on how its prosurvival function can be harnessed to promote tumor growth, malignant progression, and chemoresistance, while also influencing oncogenic microbial dysbiosis and autophagy regulation." (PMID 39188936, 2024). "Furthermore, induction of ATF6 knockdown in pre-established CCK81 s.c. xenografts also substantially inhibited tumor progression." (PMID 39324706, 2024). "Because of the tumor-promoting role of ATF6, genes down-regulated by ATF6 might play a tumor-suppressing role in HCC development." (PMID 37456776, 2023). "Therefore, genetic inhibitors targeting ATF6α can promote the apoptosis of iron cells and delay the progression of PCa in tumor cells." (PMID 37746665, 2023). "Moreover, the ATF6 signaling pathway has shown great value in the study of reversing tumor drug resistance." (PMID 37790807, 2023). "The overexpression of lncRNA MEG3 and GAS5 increases the expression of GRP78, IRE1, PERK, and ATF6, which may further trigger apoptosis to suppress tumor growth." (PMID 35625948, 2022). "By contrast, treatments by GSK621 which could activate ATF4 or by CeapinA7, an ATF6 inhibitor, significantly suppressed tumor metastasis rates." (PMID 35883579, 2022). "However, experiments performed with germ-free mice demonstrated that ATF6-activated UPR in the epithelium requires intestinal microorganisms for tumor formation." (PMID 33514437, 2021). "ATF6 also showed a mild positive correlation with SCNA scores across the majority of tumor types." (PMID 34698427, 2021). "An important question that arises is whether the link between ATF6 and AR exists in PCa patients after androgen deprivation therapy, given that their tumor still abundantly express AR." (PMID 34521429, 2021). "Overall, ATF6 plays a crucial role in promoting tumor progression and may be a promising therapeutic target, although no specific inhibitors have been identified yet." (PMID 33267910, 2020). "Furthermore, an obvious increase in GRP78, PERK, ATF6 and IRE1α expression was noted in tumour tissues with high ER stress as compared to that with low ER stress." (PMID 32672418, 2020). "ATF6 has been associated with cancer development, however its role in tumours has not been fully elucidated yet." (PMID 32111004, 2020).
tumor (continued). "Also, ADAM17, a member of the disintegrins and metalloproteases family that promotes tumor invasiveness and is found to be up-regulated in breast, gastric ovary and prostatic cancers and is induced by ATF6 in breast cancer cells." (PMID 31064137, 2019). "Indeed, Schew and Aguirre-Ghiso reported that downregulation of ATF6α prolonged the survival of nude mice bearing dormant tumour cells." (PMID 30134550, 2018). "This might be an interesting cellular model to test salicylates as chemopreventive agents in ATF6-mediated chemoresistance of tumor cells." (PMID 28835710, 2017). "In addition, p38 also induces tumor dormancy, resulting in a survival state and a quiescent state related to drug resistance through activation of the p38α-ATF6α-Rheb-mTOR pathway." (PMID 28537893, 2017). "Finally, as BiP expression frequently correlates with tumor status, chemoresistance, and prognosis and as ATF6α is the primary driver of BiP expression, targeting BiP expression via the ATFT6α pathway should be considered a therapeutic approach for cancer." (PMID 28860159, 2017). "Anti-ATF-6α antibody stained cytoplasmic in “Ctrl” tumor cells." (PMID 27015684, 2016). "In contrast, ATF-6α moved toward and reached the nucleus of tumor cells treated with Amblyomin-X." (PMID 27015684, 2016). "ATF6α was shown to be required for the survival of dormant tumor cells." (PMID 27435960, 2016). "However, accumulating evidence on ATF6-dependent tumor drug resistance has uncovered that ATF6 is another contributor to cancer drug resistance." (PMID 26622781, 2015). "The methylation of Grp94 and PDI tended to be lower in the tumor portion of KO mice with liver tumors than in the normal liver portion whereas the methylation of Chop and Atf6 tended to be higher in the tumor portion of the tumor bearing livers than the normal liver portion." (PMID 24198826, 2013). "The relative mean expression of ATF6 in tumours classified into the group 3 was 0.020 (±0.0005)." (PMID 23587192, 2013). "Characterization of pathways that may contribute to preferential expression of CHOP in the tumor identified ATF6 as a potential candidate." (PMID 24339898, 2013). "In support of the hypothesis that ER stress signals can be tumor suppressive, recent findings showed that ATF6, ATF4 and XBP-1 signaling can suppress H-Ras induced transformation in melanocytes." (PMID 17637831, 2007). "DUSP12 seems to be the most likely target based on the significantly higher expression in a subset of the tumours, but since relevant genes activated by ATF6 also are highly expressed in tumours with over-expression of ATF6, both genes are considered potential targets." (PMID 16274472, 2005). "Interestingly, both genes were also over-expressed in the tumours that showed high expression of ATF6 (LS3x, LS21 and MS8x)." (PMID 16274472, 2005). "DUSP12 was expressed significantly higher than ATF6 in a subset of the tumours." (PMID 16274472, 2005). "Therefore, inhibiting the ATF6α-Rheb-mTOR pathway in dormant tumor cells may aid in eliminating residual disease." (PMID 41438587, 2026). "To characterize the transcriptional response induced by chronic ATF6 activity and to further understand the contribution of bacteria, we performed bulk mRNA-sequencing (mRNA-seq) of colonic epithelial cells in fl/fl and tg/tg mice at the pre-tumour time point (5 week) under SPF and GF conditions." (PMID 40890536, 2025). "Additionally, ATF6α has been reported to promote tumor metastasis through ENTPD5." (PMID 40223122, 2025). "However, the exact mechanism by which ATF6α suppresses ΔNp63α to facilitate tumor metastasis remains unknown and requires further exploration." (PMID 40223122, 2025). "Similarly, ATF6 contributes to malignant tumor proliferation." (PMID 41209558, 2025). "ATF6 may more likely tend to be a tumor suppressor, whereas ATF6B appears to be more oncogenic." (PMID 35625704, 2022). "Indeed, stable depletion of ATF6 significantly reduces tumor xenograft growth in vivo." (PMID 34521429, 2021).
tumor (continued). "In our own transgenic murine model of activating transcription factor 6 (ATF6)-induced microbiota-dependent CRC (nATF6IEC), we showed a loss of mucin-filled goblet cells and a more penetrable mucus layer already preceding tumor formation in the colon of homozygous nATF6IEC mice." (PMID 33557139, 2021). "Therefore, targeting ATF6 can be considered a novel approach to prevent tumor recurrence." (PMID 32630838, 2020). "However, the ATF6 arm showed marked tumor-specific activation." (PMID 24339898, 2013). "Thus, except for LS3x, DUSP12 is significantly higher expressed than ATF6 in all the tumours that showed at least 2-fold over-expression of either or both genes, suggesting that DUSP12 may be the real target for the amplification." (PMID 16274472, 2005). "Key UPR sensors—PERK, IRE1α, and ATF6—are dysregulated in NSCLC, enabling tumor cells to evade death despite microenvironmental or treatment-induced stress." (PMID 41476609, 2025). "In colorectal cancer, phosphorylated ATF6 induces gut microbiota dysbiosis and activates the TRIF/STAT3 signaling pathway, accelerating tumor progression." (PMID 41209558, 2025). "In glioblastoma, ER stress (via ATF6 and PERK) is activated under hypoxia and DNA damage, while lysosomal impairment and mitochondrial ROS sustain tumor cell viability." (PMID 40723802, 2025). "Baseline markers such as GRP78/BiP and the XBP1 splicing ratio estimate how much a tumor is already relying on chaperone buffering or IRE1 signaling; this helps choose which arm to target (PERK/IRE1/ATF6, ROS amplification, Ca2+ handling, or proteostasis)." (PMID 41476609, 2025). "To ascertain these mechanisms, we set out to characterize the transcriptional response induced by chronic ATF6 activation in the presence (SPF) and absence (GF) of bacteria at the pre-tumour stage." (PMID 40890536, 2025). "high PLP2+ Tumor EPCs score group highly expressed ATF6, ELF1, ERG and PLAGL1 genes, while low PLP2+ Tumor EPCs score group highly expressed ATF5, TBX21, SPIB, LHX2 and JUND genes." (PMID 38482016, 2024). "Furthermore, the resistance or sensitivity of tumor cells to therapeutic agents may be associated with BiP/GRP78, a chaperone protein that binds to monomers downstream of the UPR and stabilizes IRE1, PERK, and ATF6." (PMID 39080273, 2024). "In tumor cells, the principal pathway involved is UPR, primarily orchestrated by IRE1, PERK, and ATF6." (PMID 39080273, 2024). "Moreover, exogenous ATF6 expression abrogated the tumor‐promoting effects of TPD52 depletion, whereas ATF6 knockdown in cells transfected with TPD52 largely regained its proliferative capacity, suggesting that TPD52 might function through activation of ATF6 and subsequent promotion of ER stress." (PMID 39401430, 2024). "We found that ERS can modulate tumor progression via the unfolded protein response (UPR) signaling of IRE1, PERK, and ATF6." (PMID 39080273, 2024). "Therefore, genes down-regulated by ATF6 might play a tumor-suppressing role." (PMID 37456776, 2023). "ATF6 can activate GRP78, which inhibits caspase-3 activation, maintains the stability of the ER and the internal environment, and leads to tumor resistance." (PMID 37790807, 2023). "From the figure, it can be seen that bufalin induces ERS through ATF6, PERK and IRE1 pathways, immediately followed by apoptosis of tumour cells." (PMID 38044941, 2023). "LUCRC, highly expressed in colorectal tumor tissue to promote proliferation, migration and invasion of tumor cells, is required for the expression of BiP and the cleavage of XBP1 and ATF6 to evoke UPR." (PMID 35625948, 2022). "Further analysis by GO terms, to distinguish between PERK, IRE1 and ATF6 branches of the UPR, pointed to a selective up‐regulation of PERK pathway in ERO1 KO MDAMB231* tumours." (PMID 35853086, 2022).